RUNX3 (RUNX family transcription factor 3)
Diseases named in the same sentence as RUNX3 in open-access papers (continued):
Sharing a sentence is not in itself a finding about the gene and the disease.
cervical carcinoma (7 papers, 2019 to 2025). A carcinoma arising from either the exocervical squamous epithelium or the endocervical glandular epithelium. "Although it has tumor suppressor activity, it can cause cell proliferation and migration by targeting RUNX3 in triple negative breast and cervical cancers." (PMID 40686703, 2025). "For instance, lncRNA LINC00657 inhibites cervical cancer progression via sponging miR-20a-5p and targeting RUNX3." (PMID 34552925, 2021). "RUNX3 is a tumour suppressor gene that is consistently hypermethylated in cervical cancer." (PMID 31766427, 2019). "Previous studies have shown that RUNX3 is a tumor suppressor in cervical cancer, and we found that expression of RUNX2 and RUNX3 decreased in cervical cancer cells compared to controls." (PMID 39672307, 2024). "Therefore, miR-20a-5p promotes the cytotoxicity activity of NK cells via modulating RUNX3/DR5 axis, thus inhibiting the development of cervical cancer." (PMID 35577802, 2022).
dysplasia (7 papers, 2008 to 2025). A usually neoplastic transformation of the cell, associated with altered architectural tissue patterns. "RUNX3 hypermethylation is an independent risk factor for progression of BE to high-grade dysplasia of esophagus and EAC." (PMID 25229459, 2014). "Frequent RUNX3 inactivation through promoter hypermethylation was reported in ESCC, EAC, Barrett’s metaplasia and dysplasia." (PMID 25229459, 2014). "In addition, the methylations of RUNX3 and APC have been closely correlated with an increased risk of disease progression BE to EAC, whereas that of CDKN2A is related to dysplasia, having a potential role as a biomarker in early stages of dysplasia that may lead to progression from BE to EAC." (PMID 41369383, 2025).
esophageal adenocarcinoma (7 papers, 2008 to 2025). A malignant tumor with glandular differentiation arising predominantly from Barrett mucosa in the lower third of the esophagus. "RUNX3 methylation was significantly higher in esophageal adenocarcinoma (EAC) than Barrett’s esophagus (OR = 0.35, CI = 0.20–0.59, P<0.0001)." (PMID 25229459, 2014). "RUNX3 was not expressed in normal epithelium, and rarely (<3%) in non-dysplastic BO or oesophageal adenocarcinoma epithelium." (PMID 31831860, 2020). "Therefore, we employed extended comparison methods to assess presence versus absence and there was emergence of weak intensity of epithelial nuclear RUNX3 in dysplastic BO, compared with normal mucosa (p = 0.013), non-dysplastic BO (p = 0.001) and oesophageal adenocarcinoma (p = 0.002)." (PMID 31831860, 2020).
esophageal squamous cell carcinoma (7 papers, 2011 to 2024). Esophageal squamous cell carcinoma (ESCC) is a type of esophageal carcinoma (EC) that can affect any part of the esophagus, but is usually located in the upper or middle third. "The stable CpG cg27058497 (RUNX3) has been associated with in utero tobacco smoking exposure, childhood asthma, oesophagus squamous cell carcinoma and chronic fatigue syndrome." (PMID 32114984, 2020). "Plasma levels of RUNX3 promoter hypermethylation may be a promising biomarker for the early diagnosis of esophagus squamous cell carcinoma." (PMID 25229459, 2014). "In esophageal squamous cell carcinoma (ESCC), overexpression of RUNX3 remarkably suppresses the phosphorylation of Smad2/3." (PMID 38430423, 2024). "Furthermore, it has been observed that hypermethylation of certain Wnt inhibitors, namely runt‐related transcription factor 3 (RUNX3), DKK‐3, and sFRP1, is positively associated with the recurrence of esophageal squamous cell carcinoma (ESCC)." (PMID 37901797, 2023). "The Runt-related transcription factor 3 (RUNX3) is involved in the MET’s induction by decreasing the sensitivity to the TGF-β1-induced EMT and reversing the EMT through the TGFβ/Smad signaling and by inhibiting the invasion and migration of esophageal squamous cell carcinoma (ESCC) cells." (PMID 36289908, 2022).
laryngeal carcinoma (7 papers, 2015 to 2023). Carcinoma that arises from the laryngeal epithelium. "Xu et al30 also reported that the loss of RUNX3 expression was correlated with the upregulation of miR‐106b‐5p in human laryngeal carcinoma tissues, and miR‐106b promoted the viability and invasion of laryngeal carcinoma cells by directly targeting RUNX3." (PMID 31503422, 2019). "Another study has demonstrated that miR-106b promoted the proliferation and invasion of laryngeal carcinoma cells by directly targeting RUNX3." (PMID 26473853, 2015). "miR-106b targets RUNX3 in laryngeal carcinoma cells and miR-532-5p targets RUNX3 expression in cutaneous melanoma." (PMID 26375442, 2015). "EZH2 also inhibits the expression of RUNX3 in bile duct carcinoma and laryngeal carcinoma." (PMID 33718109, 2020).
liver cancer (7 papers, 2015 to 2025). An epithelial or non-epithelial malignant neoplasm that arises from the liver. "A preclinical study using a liver cancer model demonstrated that overexpression of Runx3 in CAR-T cells significantly improved both the persistence and the infiltration of T cells within tumor tissues." (PMID 41479900, 2025). "al (2019) showed that GAS5 overexpression promoted the killing effect of NK cells on liver cancer through regulating miR-544/RUNX3." (PMID 40781182, 2025). "The relative mRNA expression levels of miR-544 and NCR1 as well as the expression of RUNX3 at protein levels were measured using qRT-PCR and western blotting in NK cells isolated from healthy volunteers and patients with liver cancer." (PMID 29636640, 2018). "Collectively, these results manifested that miR-544 promoted immune escape in liver cancer by downregulating NCR1 via targeting RUNX3." (PMID 29636640, 2018). "miR-544 promoted the immune escape of liver cancer cells by downregulating NCR1 via targeting RUNX3." (PMID 29636640, 2018). "MiR-544 was upregulated while NCR1 and RUNX3 was downregulated in NK cells of patients with liver cancer." (PMID 29636640, 2018). "Overall, our study indicated that miR-544 overexpression in activated NK cells negatively regulated NCR1 through directly targeting RUNX3, resulting in suppressive cytotoxicity against liver cancer cells." (PMID 29636640, 2018). "MiR-544 was significantly upregulated (P < 0.05) while NCR1 (P < 0.05) and RUNX3 (P < 0.05) were markedly downregulated in NK cells of liver cancer patients compared with those of healthy population, hinting that miR-544 level was negatively associated with the expression of NCR1 and RUNX3." (PMID 29636640, 2018). "In this study, the increased expression levels of miR-544 was shown to be inversely associated with the decreased expression of RUNX3 and NCR1 in NK cells separated from patients with liver cancer, while miR-544 was downregulated in IL-2 activated-NK cells in vitro." (PMID 29636640, 2018). "In liver cancer, our results showed that RUNX1 but not RUNX2 or RUNX3 was upregulated in tumor tissue in comparison with normal tissue." (PMID 32746865, 2020).
renal cell carcinoma (7 papers, 2013 to 2024). "This study aimed to investigate the associations between RUNX3 pathway signature and IO/TKI benefits in renal cell carcinoma (RCC)." (PMID 38172737, 2024). "RUNX3 expression was reported to be lower in renal cell carcinoma tissue than in adjacent normal renal tissues, and RUNX3 targeted miR-6780a-5p/E-cadherin/EMT signaling axis to suppress migration and invasion of renal carcinoma cells." (PMID 29651226, 2018). "In our previous study, we demonstrated that RUNX3 can function as a tumor suppressor by regulating cell migration, invasion and angiogenesis in renal cell carcinoma." (PMID 24475196, 2014). "In the present study, we addressed whether RUNX3 promotes tumorigenesis and metastasis in renal cell carcinoma." (PMID 29254144, 2017). "In this study, renal cell carcinoma (RCC) microarray analysis showed that the level of RUNX3 expression was lower in RCC tissue than in adjacent normal renal tissues, and was correlated with depth of invasion (pT stage) (P<0.001) and Tumor Node Metastasis (TNM) stage (P<0.001)." (PMID 29254144, 2017). "We have previously demonstrated that RUNX3 decreased the activity of MMP-9 in renal cell carcinoma." (PMID 24475196, 2014). "However, little is known about the role of RUNX3 in human renal cell carcinoma (RCC)." (PMID 23457532, 2013).
COVID-19 (6 papers, 2022 to 2024). A disease caused by infection with severe acute respiratory syndrome coronavirus 2. "Downregulation of JUNB and LEF1, and upregulation of RUNX3 was observed in all three ILC subsets from COVID-19 patients." (PMID 39026668, 2024). "For example, we found that the chemokine receptor CCR7 was downregulated with hyper-methylation at the promoter, and transcription factor RUNX3 was upregulated with hyper-methylation in the gene body in recovery COVID-19 patients." (PMID 36263014, 2022). "For instance, we observed significantly stronger enrichment of TBX21 (adjusted P = 1 × 10−224), RUNX3 (adjusted P = 1 × 10−199), TCF7L2 (adjusted P = 1 × 10−167) and ZEB1 (adjusted P = 1 × 10−118) motifs in severe COVID-19 risk variant-depleted cells." (PMID 35668323, 2022). "Additionally, an increase in the expression of MAP2K6, CBL and RUNX3 was observed in COVID-19-positive patients (p = 0.047; p = 0.00093; and p = 0.0044, respectively)." (PMID 36298734, 2022). "For example, individuals with moderate COVID-19 demonstrated lower levels of FOSL2, MAX, MAFB, IRF1, RUNX3, and HIF1A in CD14 and CD16 monocytes from other cohorts." (PMID 39712003, 2024). "Bioinformatics analyses showed upregulation of MAP2K6, CBL, RUNX3, STAT1, and JAK2 in COVID-19-positive vs. -negative patients." (PMID 36298734, 2022).
head and neck squamous cell carcinoma (6 papers, 2009 to 2024). A squamous cell carcinoma that arises from any of the following anatomic sites: lip and oral cavity, nasal cavity, paranasal sinuses, pharynx, larynx, and salivary glands. "Surprisingly, we found that RUNX3 expression level in head and neck squamous cell carcinoma (HNSCC) tissues, which is one of the most common types of human cancer, was higher than that in normal tissues by a previously published microarray dataset in our preliminary study." (PMID 19521519, 2009).
renal carcinoma (6 papers, 2012 to 2024). A carcinoma arising from the epithelium of the renal parenchyma or the renal pelvis. "The down-regulation of RUNX3 expression and its loss of function in renal cancer tissues are closely related to a poor prognosis of patients with renal cancer." (PMID 38430423, 2024). "This study has demonstrated that methylation regulates metastasis of renal cancer and is associated with TGF-β/RUNX3 pathway inhibition, with evidences from both patient renal cancer tissues and murine renal cancer xenograft models." (PMID 29651226, 2018). "RUNX3 has been found elevated in renal cancer and is associated with shorter progression-free survival, and high RUNX3 expression predicts a greater benefit of IO/TKI (immune checkpoint inhibitor combined with a lorosine kinase inhibitor) therapy compared to TKI monotherapy." (PMID 39822248, 2024). "Complementing these findings, additional research has verified that RUNX3 expression is notably suppressed in metastatic renal cancer tissues due to hypermethylation of CpG islands." (PMID 38430423, 2024). "RUNX3 gene was reported to be inactivated by aberrant methylation in gastric, colorectal, bile duct, pancreatic and renal cancers." (PMID 29651226, 2018). "This study strongly suggested that methylation played a critical role in regulating the metastasis of renal cancer, and is also associated with TGF-β/RUNX3 inhibition." (PMID 29651226, 2018). "Hypermethylation in CpG islands promotes metastasis of renal cancer and is associated with TGF-β and RUNX3 inhibition." (PMID 29651226, 2018). "In this study, we proposed that methylation inhibited TGF-β/RUNX3 pathway to affect the metastasis in renal cancer." (PMID 29651226, 2018). "In our study, we found that RUNX3 expression was reduced in metastatic renal cancer tissues compared with primary renal cancer tissues, consistent with the previous studies." (PMID 29651226, 2018). "In this study, we investigated the relationship between RUNX3 expression and clinicopathologic features, patient survival by a renal cancer tissue microarray." (PMID 29254144, 2017). "The miR-6780a-5p mimics abolished RUNX3-mediated E-cadherin upregulation and inhibition of renal cancer cell metastasis." (PMID 29254144, 2017). "Restoration of RUNX3 significantly decreased renal carcinoma cell migration and invasion capacity compared with controls." (PMID 23457532, 2013). "Our study also provided direct evidence that RUNX3 functions as a tumor suppressor in human renal cancer." (PMID 22457727, 2012). "Restoration of RUNX3 significantly decreased renal carcinoma cell migration and invasion capacity." (PMID 29651226, 2018). "As it has been strongly indicated that RUNX3 regulated the renal cancer cell metastasis in the previous studies, we studied the role of RUNX3 in renal cancer metastasis by comparison of metastatic and primary renal cancer." (PMID 29651226, 2018). "More importantly, it strongly indicated that the malignancy of metastatic renal cancer tissues could be weakened by introducing higher expressions of RUNX3 and TGF-β by inhibiting their promoter methylation." (PMID 29651226, 2018). "Decreased expression of certain tumor suppressive genes get the ability to promote cell motility and invasion, and we suspected that RUNX3 might inhibit renal cancer cell migration and invasion." (PMID 29254144, 2017). "Thus, RUNX3 targeted the miR-6780a-5p/E-cadherin/EMT signaling axis to suppress renal carcinoma cell metastasis." (PMID 29254144, 2017). "Thus, RUNX3 targeted the miR-6780a-5p/E-cadherin/EMT signaling axis to suppress renal carcinoma cell migration and invasion." (PMID 29254144, 2017). "To determine whether RUNX3 upregulated E-cadherin through miR-6780a-5p, we inserted miR-6780a-5p mimics into renal cancer cells stably overexpressing RUNX3." (PMID 29254144, 2017).
renal carcinoma (continued). "In addition, we found that restoration of RUNX3 expression in human renal cancer cells dramatically decreased cell migration and invasion abilities by down-regulating MMP-9 expression." (PMID 23457532, 2013). "RUNX3 staining and clinicopathological characteristics of 75 renal cancer patients." (PMID 23457532, 2013). "Our proliferation results demonstrated that RUNX3 might inhibit the renal cancer cell growth by inducing G1/S arrest." (PMID 22457727, 2012). "Therefore, we might infer that RUNX3 induced growth suppression of renal cancer cells partially by regulating various proteins which were controlling G1 to S progression." (PMID 22457727, 2012). "RUNX3 and TGF-β levels were decreased in metastatic renal cancer tissues as a result of their CpG methylation." (PMID 29651226, 2018). "Next, we compared the changes in methylation levels of RUNX3 and TGF-β in metastatic renal cancer tissues, with primary renal cancer tissues as the control." (PMID 29651226, 2018). "In all, experimental evidence confirmed that RUNX3 was down-regulated in CCRCC and appeared to be a potent growth and metastasis inhibitor in renal cancer cells." (PMID 22457727, 2012). "Furthermore, the decreased expressions of RUNX3 and TGF-β in metastatic renal cancer compared with the primary renal cancer were confirmed by Western blot." (PMID 29651226, 2018). "RUNX3 and TGF-β may also function as biomarkers for renal cancer metastasis prediction, and for selection of patient specific treatment plans." (PMID 29651226, 2018). "Elevated CpG methylation levels of RUNX3 and TGF-β were detected in metastatic cancer tissues by qMSP, while reduced global DNA methylation levels of RUNX3 and TGF-β were observed compared with primary renal cancer tissues by quantitative methylation real-time PCR." (PMID 29651226, 2018). "To investigate the roles of RUNX3 and TGF-β in metastatic renal cancer, we established two murine models, metastatic and primary renal cancer xenograft models by injection of 1 × 104 corresponding renal cancer cells into the left forelegs of mice, respectively." (PMID 29651226, 2018). "However, the relationship between RUNX3 and methylation in renal cancer has not been studied." (PMID 29651226, 2018).
ulcerative colitis (6 papers, 2014 to 2022). An inflammatory bowel disease involving the mucosal surface of the large intestine and rectum. "According to these findings, it is interesting to mention that in patients affected by ulcerative colitis (UC), an increased DNA methylation of Runt-related transcription factor 3 (RUNX3), Protease activated receptor 2 (PAR2) and E-cadherin genes have been found." (PMID 33602320, 2021). "We aimed to analyze the dependence of RUNX3 promoter 2 (P2) methylation level on: age, sex, body mass index (BMI), C-reactive protein (CRP), serum albumin, disease duration, Pediatric Ulcerative Colitis Activity Index (PUCAI), the Paris classification, and exposure to medications." (PMID 36140736, 2022).
Autoimmunity (5 papers, 2013 to 2024). The occurrence of an immune reaction against the organism's own cells or tissues. "RUNX3 belongs to the runt domain family of transcription factors, which are key regulators of lineage-specific gene expression and more recently are found to be linked to human autoimmunity." (PMID 23637848, 2013). "Overall, RUNX3 is a gene clearly playing a role in immunity that warrants a fundamental study in the context of autoimmunity, going beyond the traditionally explored context of RUNX3 and gastrointestinal oncogenesis." (PMID 37371794, 2023). "Knowing that expression of RUNX3 may orchestrate immune-cell plasticity and differentiation, it would be useful to understand whether epigenetic hallmarks, such as DNA hypermethylation, play a pivotal role in triggering and/or maintaining autoimmunity in children." (PMID 36140736, 2022). "Importantly, the RUNX3 transcriptional activity is induced during the Epstein–Barr virus (EBV) infection of B cell immortality, leading to the repression of RUNX1, with both factors considered as interesting transcriptional regulators of autoimmunity." (PMID 30096841, 2018).
clear cell renal cell carcinoma (5 papers, 2012 to 2023). "In another report, expression of RUNX3 was significantly decreased in 75 cases of clear cell renal cell carcinoma tissues, and RUNX3 inhibited the proliferative and metastatic abilities of clear cell renal cell carcinoma cells by regulating cyclins and TIMP1." (PMID 29651226, 2018). "Our TF family member analysis showed that RUNX1, RUNX2, and RUNX3 were all within the top 5 % of TFs correlated with hypomethylation of RUNX-containing enhancer probes in clear cell renal carcinoma (KIRC) a, b." (PMID 25994056, 2015). "Here we presented that the expression of RUNX3 was significantly decreased in 75 cases of clear cell renal cell carcinoma (CCRCC) tissues (p<0.05)." (PMID 22457727, 2012). "The effect of RUNX3 on the epithelial–mesenchymal transition in clear-cell renal cell carcinoma (CCRCC) remains unclear." (PMID 36518886, 2022).
endometriosis (5 papers, 2018 to 2025). The growth of functional endometrial tissue in anatomic sites outside the uterine body. "RUNX3 was found to be closely associated with the malignant transformation of EM, with its expression level in Endometriomas being significantly higher than in Endometriosis, emphasizing its potential as a therapeutic target for EM." (PMID 41159025, 2025). "Besides, the degree of RUNX3 hypermethylation and decreased RUNX3 protein expression in the eutopic endometrium from the EAOC group was significantly higher than that in the endometriosis (EM) and control endometrium (CE) groups." (PMID 29780815, 2018).